NSUN5 (NOP2/Sun RNA methyltransferase 5)
Description:
S-adenosyl-L-methionine-dependent methyltransferase that specifically methylates the C(5) position of cytosine 3782 (m5C3782) in 28S rRNA. m5C3782 promotes protein translation without affecting ribosome biogenesis and fidelity. Required for corpus callosum and cerebral cortex development (By similarity).
Synonyms: NOL1R; NSUN5A; WBSCR20; WBSCR20A; p120(NOL1); FLJ10267; Ynl022cL; NOL1; p120
Tractability: PROTAC: ubiquitination databases record sites on it; its protein half-life has been measured.
Target class: Enzyme; Transferase
Gene: Protein-coding gene on chromosome 7 (73,302,516 to 73,308,867, reverse strand). Ensembl gene ENSG00000130305.
Subcellular location: Nucleus, nucleolus
Subcellular location (Human Protein Atlas): Nucleoli; Nucleoplasm
Gene Ontology:
Molecular function: RNA binding; rRNA (cytosine-C5-)-methyltransferase activity; methyltransferase activity; RNA methyltransferase activity
Biological process: positive regulation of translation; rRNA base methylation; cerebral cortex development; cognition; corpus callosum development; oligodendrocyte development; regulation of myelination
Cellular component: nucleolus; nucleoplasm
Genetic constraint (gnomAD): Loss-of-function variants: 39 observed, 51.51 expected, observed/expected ratio (o/e) 0.76, 90% interval 0.58 to 0.99. The upper end of that interval is the gene's LOEUF score, 0.99, which puts it in group 4 of 6, group 1 being the genes least tolerant of losing a copy. Missense variants: 526 observed, 616.62 expected, observed/expected ratio (o/e) 0.85, 90% interval 0.79 to 0.92. Synonymous variants: 266 observed, 275.96 expected, observed/expected ratio (o/e) 0.96, 90% interval 0.87 to 1.07.
Homologues: Orthologues: chimpanzee NSUN5 (99% identical), macaque NSUN5 (97% identical), dog NSUN5 (85% identical), guinea pig NSUN5 (85% identical), pig NSUN5 (85% identical), mouse Nsun5 (84% identical), rat Nsun5 (83% identical), tropical clawed frog nsun5 (56% identical), zebrafish nsun5 (53% identical), Caenorhabditis elegans nsun-5 (33% identical), Drosophila melanogaster Nsun5 (30% identical). Paralogues in human: NOP2 (26% identical), NSUN6 (18% identical).
Diseases named in the same sentence as NSUN5 in open-access papers:
NSUN5 is named in the same sentence as 46 diseases in open-access papers, as found by Europe PMC text mining. Sharing a sentence is not in itself a finding about the gene and the disease. The quoted sentences say what the papers report.
glioma (28 papers, 2019 to 2026). A benign or malignant brain and spinal cord tumor that arises from glial cells (astrocytes, oligodendrocytes, ependymal cells). "In this study, we systematically analyzed the expression and functional associations of NSUN5 in glioma using data from The Cancer Genome Atlas (TCGA) and the Chinese Glioma Genome Atlas (CGGA) databases." (PMID 41555554, 2026). "NSUN5 expression is significantly upregulated in glioma and is positively associated with tumor malignancy and poor prognosis." (PMID 41555554, 2026). "High NSUN5 expression is closely associated with poor prognosis in glioma patients, highlighting its potential as a prognostic biomarker and therapeutic target." (PMID 41555554, 2026). "NSUN5, as an RNA methyltransferase, plays a key role in the onset and progression of gliomas, and its abnormal expression is closely associated with patient survival outcomes." (PMID 41555554, 2026). "In gliomas, NSUN5 directly interacts with CTNNB1 chromium-associated RNA (caRNA) and deposits m5C on it." (PMID 41462962, 2025). "Most importantly, epigenetic inactivation of NSUN5 is a hallmark of long-term survival for patients with glioma." (PMID 41462962, 2025). "Glioma cells feature NSUN5 gene silencing associated with the high methylation of cancer-specific promoter CpG islands." (PMID 41462962, 2025). "NSUN5 downregulates β-catenin by promoting the degradation of its mRNA, enhancing the phagocytic activity of tumor-associated macrophages (TAMs) in gliomas." (PMID 41462962, 2025). "Loss of m5C methyltransferase NSUN5 in gliomas correlated with long-term survival of glioma patients." (PMID 37403043, 2023). "Epigenetic loss of NSUN5 expression in gliomas leads to rRNA cytosine hypomethylation and to increased translation of survival factors, rendering glioma cells sensitive to substrates of the stress-related enzyme NAD(P)H quinone dehydrogenase 1 (NQO1)." (PMID 33461542, 2021). "The authors suggested that NSUN5 loss contributes to the protection of glioma cells from stress conditions." (PMID 33564819, 2021). "DNA methylation-associated epigenetic silencing of NSUN5 is observed in human gliomas, and it helps glioma cells overcome hostile stress conditions." (PMID 33912441, 2021). "Another study demonstrated that NSUN5 epigenetic inactivation is a hallmark of long-term survival for patients with glioma." (PMID 33912441, 2021). "The ultimate result of their work showed thatin glioma cells, the epigenetic loss of NSUN5, in a frame of general restriction of the protein synthesis, induces the selective synthesis of specific proteins." (PMID 32316617, 2020). "TCGA RNA-sequencing data showed that NSUN5 hypermethylation was associated with transcript downregulation across glioma samples (Spearman’s rank correlation, ρ = − 0.7, P < 10−5)." (PMID 31428936, 2019). "Overall, these results indicate that cancer-specific promoter CpG island hypermethylation-associated silencing of the NSUN5 gene occurs in glioma cells." (PMID 31428936, 2019). "Most importantly, NSUN5 epigenetic inactivation is a hallmark of glioma patients with long-term survival for this otherwise devastating disease." (PMID 31428936, 2019). "In conclusion, NSUN5 loss in glioma provides a link between an epigenetic event, the promoter CpG island hypermethylation of its promoter, and an epitranscriptomic event, the hypomethylated status of the C3782 position of the human 28S rRNA." (PMID 31428936, 2019). "We observed that NSUN5 hypermethylation was associated with increased overall survival (OS) in all glioma grades in the TCGA cohort [log-rank; P < 10−5; hazard ratio (HR) = 5.17, 95% CI = 2.78–9.61]." (PMID 31428936, 2019). "Once we had demonstrated the existence of NSUN5 CpG island hypermethylation-associated transcriptional loss in glioma cell lines, we studied its contribution to the growth of these cells." (PMID 31428936, 2019).
glioma (continued). "Data-mining of microarray expression results showed that NSUN5 hypermethylation was associated with transcript downregulation in the glioma cell lines." (PMID 31428936, 2019). "NSUN5 methylation is associated with extended PFS in low-grade gliomas (LGG, n = 183) (log-rank; P value 10−5; HR = 5.07; 95% CI = 3.46–7.41) and glioblastoma (GBM, n = 235) (log-rank; P value 10−5; HR = 2.14; 95% CI = 1.58–2.91)." (PMID 31428936, 2019). "Altogether, these data are consistent with the idea that the loss of NSUN5 in glioma cells restricts general protein synthesis while activating the selective synthesis of specific stress-related proteins such as NQO1." (PMID 31428936, 2019). "Here, we report that human glioma cells undergo DNA methylation-associated epigenetic silencing of NSUN5, a candidate RNA methyltransferase for 5-methylcytosine." (PMID 31428936, 2019). "TCGA RNA-sequencing data showed NSUN5 hypermethylation to be associated with transcriptional downregulation in low- and high-grade gliomas." (PMID 31428936, 2019). "This study focuses on the RNA methyltransferase NSUN5, which not only possesses molecular diagnostic potential but may also contribute to glioma progression through modulation of the TME, thereby offering a novel target for precision therapy." (PMID 41555554, 2026). "Therefore, NSUN5 epigenetic silencing is considered a protective factor in gliomas and is associated with better prognosis." (PMID 40370440, 2025). "In contrast to NSUN7, NSUN5 silencing is a hallmark of glioma patients with long-term survival." (PMID 37369946, 2023). "Additionally, in glioblastomas, the expression of NSUN5 is correlated with poor survival, while in low-grade gliomas, the high expression of NSUN7 is associated with a shorter survival time." (PMID 36360287, 2022). "Despite being a tumour suppressor, loss of NSUN5 correlates with good prognosis in gliomas; while NSUN5 helps to safeguard against stress conditions in the early stages of tumorigenesis, it is likely that its loss limits the proliferation potential of fully transformed glioma cells." (PMID 33564819, 2021). "Furthermore, NSUN5 epigenetic inactivation was associated with a better prognosis for glioma patients." (PMID 32974125, 2020). "The finding that NSUN5 epigenetic silencing was associated with NQO1 overexpression prompted us to study whether these glioma cells might be more vulnerable to compounds targeting this particular stress-related protein." (PMID 31428936, 2019). "We examined whether other genetic and epigenetic alterations of clinical relevance in glioma helped define patients with NSUN5 methylation-associated extended survival." (PMID 31428936, 2019). "Therefore, in‐depth research into the diagnostic, prognostic evaluation, and therapeutic roles of NSUN5 in gliomas could bring new hope for improving patient survival rates." (PMID 41555554, 2026). "However, the role and underlying mechanisms of NSUN5 in gliomas are still unclear." (PMID 41555554, 2026). "Moreover, and specifically for glioma, this apparent paradox is tightly linked to another seemingly controversial observation of a condition—NSUN5 depletion via promoter hypermethylation—which favours tumour growth but at the same time is a good prognostic factor." (PMID 32316617, 2020). "Thus, we wondered whether the loss of the methylated site in the 28S rRNA mediated by NSUN5 epigenetic inactivation in glioma cells could act in this manner." (PMID 31428936, 2019). "Secondly, although studies have preliminarily uncovered the function of NSUN5 in tumors, its specific molecular mechanisms, especially its role in gliomas, still need to be further elucidated." (PMID 41555554, 2026). "Utilizing RT‐Qpcr and, we investigated the expression of NSUN5 in glioma tissues, with results consistent with RNA sequencing data, indicating higher expression of NSUN5 in glioma." (PMID 41555554, 2026).
glioma (continued). "In glioma, we observed that NSUN5 expression was significantly elevated across patients of different sexes, ages, and body weights." (PMID 41555554, 2026). "In the CGGA database, NSUN5 expression was higher in patients with high‐grade gliomas, IDH‐wildtype gliomas, and those without 1p/19q codeletion." (PMID 41555554, 2026). "Although NSUN5 has excellent potential as a prognostic marker in gliomas, it still faces several challenges." (PMID 41555554, 2026). "This study systematically analyzed the expression levels, clinical features, prognostic value, immune‐related roles, drug sensitivity, and biological functions of NSUN5 in glioma based on the CGGA and TCGA databases." (PMID 41555554, 2026). "The study identified potential mechanisms through which NSUN5 contributes to poor outcomes in glioma patients, offering insights for future targeted therapies." (PMID 41555554, 2026). "The HPA online database also revealed that NSUN5 expression was notably upregulated in glioma patients." (PMID 41555554, 2026). "First, we analyzed the CPTAC database and found that NSUN5 expression was significantly increased in colorectal cancer, clear cell renal carcinoma, lung cancer, pancreatic cancer, head and neck cancer, gliomas, and liver cancer." (PMID 41555554, 2026). "While NSUN2 and NSUN4 are highly expressed in glioma, single-cell bioinformatic analysis has revealed that malignant cells present the lowest NSUN5 expression levels among the different cell types that make up the tumour mass." (PMID 40860147, 2025). "In in vivo glioma models, NSUN5 exhibits high methylation in CpG island promoter regions, leading to reduced transcript levels and epigenetic silencing." (PMID 40370440, 2025). "NSUN5, in particular, is known to regulate ribosomal stress responses and translational control, facilitating glioma adaptation to stress and correlating with poor prognosis." (PMID 40565233, 2025). "In gliomas, Nsun5 modifies cytoplasmic RNA through 5-methylcytosine (m5C) modification, which is then oxidized by TET2 into 5-hydroxymethylcytosine (5hmC), leading to RNA degradation and inhibition of tumor growth." (PMID 39769404, 2024). "NSUN5‐mediated rRNA modification plays a critical role in glioma progression and enhances therapeutic responses." (PMID 38797935, 2024). "According to a recent study on gliomas, five genes related to m5C methyltransferase were identified to construct a risk signature (5MM) and were used to predict glioma prognosis, including NOP2, NSUN4, NSUN5, NSUN6 and NSUN7." (PMID 36637205, 2023). "Few years ago, we also described the epigenetic silencing of NSUN5 by gene-promoter methylation in glioma." (PMID 37369946, 2023). "For example, epigenetic changes in NSUN5 have been reported to predict the prognoses of patients with gliomas." (PMID 37263638, 2023). "The epigenetic deletion of NSUN5 in glioma downregulates rRNA methylation levels and subsequently increases growth factor translation, making glioma cells resistant to the stress-related enzyme NAD(P)H quinone dehydrogenase 1 sensitive." (PMID 36360287, 2022). "In the in vivo glioma models, NSUN5 showed hypermethylation of the CpG island promoter, leading to a reduction in transcripts and epigenetic silencing." (PMID 35562754, 2022). "In particular, NSUN5 silencing in glioma reduces global protein synthesis but results in the selective translation of specific mRNA to increase cell survival of stress conditions." (PMID 33946178, 2021). "Despite its pro-proliferative effect, in human glioma tumors the NSUN5 gene acts as an onco-suppressor and was found to be silenced by DNA methylation." (PMID 33946178, 2021). "The results showed that NSUN4, NSUN7, DNMT1, DNMT3B, DNMT3A, NOP2 and NSUN5 were negatively correlated with the overall survival of low‐grade glioma, while NSUN6 was positively correlated with the overall survival." (PMID 33400376, 2021).
glioma (continued). "For example, the well-identified “writer” NSUN5 exhibits tumor-suppressing characteristics in gliomas." (PMID 33912441, 2021). "We obtained six genes associated with prognosis (P < 0.01), among which NOP2, NSUN2, NSUN4, NSUN5, and NSUN7 acted as risk factors (HR > 1), and NSUN6 played a protective role (HR < 1) in gliomas." (PMID 32974125, 2020). "We also studied the stable knockdowns of NSUN5 by the short hairpin RNA (shRNA) method in the NSUN5-expressing and unmethylated glioma cell lines DBTRG-05MG and CAS-1." (PMID 31428936, 2019). "We observed the enrichment of NSUN5 hypermethylation in low-grade gliomas (34%, 180 of 527) relative to GBM (6%, 10 of 154) (Fisher’s exact test, P = 3.8 10−9)." (PMID 31428936, 2019). "We further expanded this initial validation cohort with the inclusion of two independent glioma cohorts of 303 patients, where NSUN5 methylation status is available from the same DNA methylation microarray used in the TCGA glioma cases." (PMID 31428936, 2019). "NSUN5 methylation-mediated overexpression of NQO1 can also constitute a therapeutic opportunity in these gliomas, because they become more sensitive to ROS-induced death upon the use NQO1-bioactivatable molecules." (PMID 31428936, 2019). "The study of 16 patient-derived xenograft (PDX) from primary gliomas engrafted in nude mice showed that NSUN5 was hypermethylated in three cases (19%)." (PMID 31428936, 2019). "Beyond adult gliomas, we also detected NSUN5 hypermethylation in pediatric brain tumors, such as diffuse intrinsic pontine glioma (DIPG) (50%, 5 of 10) and medulloblastoma (25%, 2 of 8)." (PMID 31428936, 2019). "Glioma cells with restored NSUN5 expression presented RNA abundance differences in less than 2% transcripts (255 upregulated and 244 downregulated) remaining the 98% transcript abundance unchanged (absolute log2 fold change > 2)." (PMID 31428936, 2019). "Once we had determined in glioma cell lines and mouse models the effects of NSUN5 epigenetic silencing, we studied the impact of NSUN5 promoter CpG island hypermethylation in human primary gliomas." (PMID 31428936, 2019). "In glioma tissues, low expression levels of NSUN5 are more pronounced in low‐grade gliomas." (PMID 41555554, 2026). "Moreover, we found that OS in glioma patients significantly decreases as NSUN5 expression increases." (PMID 41555554, 2026). "As a potential prognostic marker and therapeutic target, NSUN5 may provide critical insights for personalized glioma treatment and advance the precision of clinical interventions." (PMID 41555554, 2026). "Interestingly, glioma-specific regulators such as NSUN5 and TRDMT1 exhibited localized enrichment in oligodendrocytes and fibroblasts, suggesting their roles in neuro-glial remodeling and stress adaptation." (PMID 40565233, 2025). "Intriguingly, this study revealed that NSUN5 could act as an immune therapy target to transform glioma into a “warm tumour” and lead to impressive therapeutic outcomes when NSUN5 is restored in IDH1-R132H mutant glioma cells." (PMID 40860147, 2025). "Similarly, the epigenetic silencing of NSUN5 results in tumour suppression and an unmethylated C3782 in 28S rRNA in glioma." (PMID 38797935, 2024). "Therefore, NSUN5 epigenetic silencing is a protective factor in gliomas and is correlated with a better prognosis." (PMID 35562754, 2022). "Recently, it has been shown that NSUN5 is lost from a significant subgroup of human gliomas." (PMID 33564819, 2021). "However, this makes them more susceptible to specific therapies, thus contributing to the better prognosis of glioma patients characterized by NSUN5 silencing." (PMID 32316617, 2020). "Given the known relation between glioma grade and clinical outcome, we wondered whether NSUN5 hypermethylation also conferred any prognostic value." (PMID 31428936, 2019).